ACTL7A (actin like 7A)
Description:
Essential for normal spermatogenesis and male fertility. Required for normal sperm head morphology, acroplaxome formation, acrosome attachment, and acrosome granule stability. May anchor and stabilize acrosomal adherence to the acroplaxome at least in part by facilitating the presence of F-actin in the subacrosomal space (By similarity). May play an important role in formation and fusion of Golgi-derived vesicles during acrosome biogenesis.
Synonyms: SPGF86
Tractability: No criterion of Open Targets' tractability assessment is met for any kind of drug.
Gene: Protein-coding gene on chromosome 9 (108,862,266 to 108,863,756, forward strand). Ensembl gene ENSG00000187003.
Subcellular location: Cytoplasm, cytoskeleton; Golgi apparatus; Cytoplasm; Nucleus; Cytoplasmic vesicle, secretory vesicle, acrosome
Subcellular location (Human Protein Atlas): Perinuclear theca
Gene Ontology:
Molecular function: protein binding; structural constituent of cytoskeleton; structural molecule activity
Biological process: acrosome assembly; fertilization; spermatid development; cytoskeleton organization
Cellular component: acrosomal vesicle; nucleus; perinuclear theca; protein-containing complex; cytoplasm; cytoskeleton; Golgi apparatus; male germ cell nucleus; motile cilium
Genetic constraint (gnomAD): Loss-of-function variants: 27 observed, 31.49 expected, observed/expected ratio (o/e) 0.86, 90% interval 0.63 to 1.18. The upper end of that interval is the gene's LOEUF score, 1.18, which puts it in group 5 of 6, group 1 being the genes least tolerant of losing a copy. Missense variants: 566 observed, 601 expected, observed/expected ratio (o/e) 0.94, 90% interval 0.88 to 1.01. Synonymous variants: 259 observed, 254.78 expected, observed/expected ratio (o/e) 1.02, 90% interval 0.92 to 1.13.
Homologues: Orthologues: chimpanzee ACTL7A (99% identical), macaque ACTL7A (99% identical), pig ACTL7A (88% identical), dog ACTL7A (88% identical), rat Actl7a (86% identical), mouse Actl7a (86% identical), guinea pig ACTL7A (85% identical), rabbit ACTL7A (83% identical). Paralogues in human: ACTL7B (54% identical), ACTL9 (39% identical), ACTA2 (38% identical), ACTB (38% identical), ACTG2 (38% identical), ACTC1 (37% identical), ACTG1 (37% identical), ACTA1 (37% identical), ACTBL2 (37% identical), ACTRT2 (31% identical), ACTR1A (31% identical), ACTR1B (31% identical), and 14 more.
Diseases named in the same sentence as ACTL7A in open-access papers:
ACTL7A is named in the same sentence as 8 diseases in open-access papers, as found by Europe PMC text mining. Sharing a sentence is not in itself a finding about the gene and the disease. The quoted sentences say what the papers report.
Infertility (6 papers, 2016 to 2025). "More recently, a homozygous missense mutation of the actin-like 7A (ACTL7A) gene was identified by whole-exome sequencing in two infertile brothers, and a corresponding mutated mouse model was generated." (PMID 40649994, 2025). "ACTL7A-deficient sperm showed reduced levels of PLCζ, a sperm-borne oocyte-activation factor, and artificial oocyte activation overcame the infertility caused by ACTL7A deficiency." (PMID 37800308, 2023). "This indicated that ICSI-AOA remains an effective technique to rescue infertility caused by defective ACTL7A, even in the complete absence." (PMID 37667331, 2023). "Homozygous ACTL7A missense mutation causes sperm acrosomal defects and infertility in human and mouse." (PMID 37800308, 2023). "Previous studies have reported that ICSI-AOA can successfully rescue infertility due to Actl7a/ACTL7A with different mutations." (PMID 37667331, 2023). "In order to further understand the underlying cause behind the infertility of KO mice, we tested the ability of Actl7a−/− sperm to undergo capacitation." (PMID 36734600, 2023). "It has been reported that ICSI-AOA can successfully rescue infertility caused by mutated Actl7a/ACTL7A, including missense mutation and compound heterozygous variants." (PMID 37667331, 2023). "Our previous study had reported infertile patients with a homozygous missense mutation of ACTL7A (c.733G > A, p.Ala245Thr), leading to extremely reduced expression of ACTL7A protein." (PMID 37667331, 2023). "In fact, changes in the expression or intracellular position of PLCζ in spermatozoa are associated with subfertility or even infertility owing to impaired embryonic development, and ACTL7A protein levels were shown to be significantly reduced in sperm samples presenting poor embryo quality." (PMID 40649994, 2025). "Amino acid position 373 in the ACTL7A protein is a mutational hot spot, also affected by other reported variants: p.Arg373His in a patient from a consanguineous family suffering from the same infertility phenotype." (PMID 39411542, 2024). "Two different Actl7a−/− mouse models support our findings, showing that an abnormal Actl7a protein in mice sperm causes infertility, compromised acrosome morphology, reduced PLCζ protein content, and impaired Ca2+ release, leading to total FF after both ICSI and IVF." (PMID 39411542, 2024). "ICSI-AOA remains an effective technique to rescue infertility caused by the deletion of ACTL7A." (PMID 37667331, 2023). "Interestingly, five polymorphisms in ACTL7B (and six in ACTL7A) were detected in a cohort of Japanese infertile male individuals, suggesting that ACTL7B plays a role in fertility." (PMID 37800308, 2023). "Additionally, ICSI-AOA remained an effective technique to rescue infertility caused by the complete deletion of ACTL7A." (PMID 37667331, 2023). "We have focused on the spermatozoa-specific expression protein ACTL7a for many years and have developed an enzyme-linked immunosorbent assay (ELISA) to detect the concentration of anti-ACTL7a antibodies in fertile sera (n = 267) and infertile sera (n = 193)." (PMID 26957350, 2016). "Measuring sperm volume can be another effective method for determining infertility owing to defective ACTL7A." (PMID 37667331, 2023). "The concentration of anti-ACTL7a was higher in the fertile female group (than in the fertile male group) but significantly higher in the infertile male group." (PMID 26957350, 2016). "In this study, we developed an enzyme-linked immunosorbent assay (ELISA) to accurately detect the concentration of anti-ACTL7a antibodies in hundreds of fertile or infertile human sera collected from 2011 to 2015." (PMID 26957350, 2016). "This provides a basis for clinical treatment of infertility due to any defective ACTL7A." (PMID 37667331, 2023). "Supporting the results of previous studies, Actl7a-mutated sperm failed to activate the oocyte, leading to infertility." (PMID 37800308, 2023).
Infertility (continued). "When Actl7a KO male mice were paired with WT female mice, complete infertility was observed." (PMID 36734600, 2023). "The best cut-off determined by the ROC curves between the fertile group and the infertile group was 0.3449 × 10−1 μg/μL, showing that the anti-ACTL7a antibodies in serum with a concentration over 0.3449 × 10−1 μg/μL were considered positive according to the ELISA." (PMID 26957350, 2016). "We found that the concentration of anti-ACTL7a antibodies was significantly higher in the infertile sera (than in the fertile sera, P < 0.0001) and much higher in the TAT ≥ 16 infertile sera." (PMID 26957350, 2016). "When antigens against the universal expression protein ACTIN were detected in the sera, as opposed to the spermatozoa-specific expression protein ACTL7a, they were found to be higher in the fertile sera than in the infertile sera." (PMID 26957350, 2016). "In contrast to the anti-ACTL7a antibodies, the average concentrations of the anti-ACTIN antibodies declined from 0.23 ± 0.01 × 10−1 μg/μL in fertile sera to 0.16 ± 0.01 × 10−1 μg/μL in infertile sera (P < 0.0001)." (PMID 26957350, 2016). "Although the sera collected from the infertile (TAT ≥ 16) group had higher levels of TAT, approximately one-sixth of the subjects tested negative for the anti-ACTL7a antibody based on ELISA; the female infertilities (TAT ≥ 16) contributed greatly to the negative results." (PMID 26957350, 2016).
male infertility (6 papers, 2016 to 2025). The inability of the male to effect fertilization of an ovum after a specified period of unprotected intercourse. "Loss of SPACA1 and ACTL7A induce abnormal acrosome formation in spermatogenesis and male infertility." (PMID 38597936, 2024). "ACTL7A variants cause acrosome detachment responsible for male infertility and early embryonic arrest." (PMID 37667331, 2023). "Actin-like 7A (ACTL7A) is one such factor for which deleterious polymorphisms have recently been shown to cause human male infertility." (PMID 36734600, 2023). "Subsequently, several reports had shown that different variants in ACTL7A were associated with male infertility, displaying different degrees of acrosome abnormalities." (PMID 37667331, 2023). "The genetic analysis of ACTL7A can be an efficient method to identify previously neglected cases of unexplained male infertility." (PMID 37667331, 2023). "The average concentration of the anti-ACTL7a antibodies in the male infertility (TAT ≥ 16) group were much higher than the concentrations in the female infertility (TAT ≥ 16) group (P = 0.0038)." (PMID 26957350, 2016). "ICSI-AOA is an effective technique to rescue male infertility resulting from ACTL7A deletion." (PMID 37667331, 2023). "However, the average concentrations of the anti-ACTL7a antibodies in the male infertility subjects (n = 43) were much higher (approximately 50% higher, P < 0.0001) than the concentrations in the female infertility subjects (n = 150)." (PMID 26957350, 2016). "Most recently, the depicted phenotype of peeling acrosomes has been described in humans where coding point mutations in the actin-like 7A (ACTL7A) and ACTL7C (aka ACTL9) genes have been identified as pathogenic variants of significance in cases of complete human male infertility." (PMID 36734600, 2023).
angina (1 paper, 2025). "Similarly, the methylation levels at cg14480594 in the ACTL7A gene, cg17387122 in the MICAL3 gene, and cg02787562 in the SUN1 gene, which are associated with PM10, were significantly positively correlated with the risk of MI, angina, and HF, respectively (FDR < 0.05)." (PMID 41420191, 2025).
asthenozoospermia (1 paper, 2016). "The high concentrations of anti-ACTL7a antibodies in the asthenozoospermia or Azoospermia cases reflect the deleterious effects of ASAs on spermatozoa." (PMID 26957350, 2016). "The average concentration of anti-ACTL7a antibodies in the six asthenozoospermia subjects was 1.4800 ± 0.2332 μg/μL, which was much higher than for the fertile males, and all six of the asthenozoospermia sera (100%) were positive and five (83.33%) were strongly positive." (PMID 26957350, 2016).
Azoospermia (1 paper, 2016). Absence of any measurable level of sperm,whereby spermatozoa cannot be observed even after centrifugation of the semen pellet. "The average concentrations of the anti-ACTL7a antibodies in the six Azoospermia were 0.6768 ± 0.0644 μg/μL, and all of them (100%) were positive." (PMID 26957350, 2016).
ACTL7A also shares sentences with these, for which no sentence is quoted: breast carcinoma (1 paper); female infertility (1); oral cancers (1).